AR (androgen receptor)
Diseases named in the same sentence as AR in open-access papers (continued):
Sharing a sentence is not in itself a finding about the gene and the disease.
breast carcinoma (continued). "Breast cancer-free survival in relation to AR diplotypes was thus analysed in the 569 patients with invasive cancers and without preoperative treatment." (PMID 22033271, 2011). "In this study, we explored the therapeutic implications of the AR-ERK feedback loop in molecular apocrine breast cancer." (PMID 21457548, 2011). "Although unable to interact with FlnA, the mutant AR still mediates androgen-induced DNA synthesis as shown by BrdU incorporation analysis of AR-negative human mammary cancer-derived MDA-MB231 cells ectopically expressing this mutant." (PMID 21359179, 2011). "Additional work is necessary to elucidate the specific mechanisms by which the androgens and AR influences breast cancer cells proliferation and apoptosis." (PMID 20831839, 2010). "On the other hand AR appears as a promising predictive biomarker for response to neoadjuvant chemotherapy in locally advanced breast cancer patients." (PMID 20831839, 2010). "Consistent with a role for AR in breast cancer outcome, AR potently inhibited ERα transactivation activity and 17β-estradiol-stimulated growth of breast cancer cells." (PMID 20831839, 2010). "Considerably little is known about the biological role and clinical significance of androgen and its receptor (AR) expression in breast cancer." (PMID 20831839, 2010). "Considerably little is known about the biological role and clinical significance of androgen receptor expression in breast cancer." (PMID 20831839, 2010). "The objectives of this study were to characterize AR-CAG repeat genotypes in a cohort of women with breast cancer and to determine the influence of AR on response to neoadjuvant chemotherapy and clinical outcome." (PMID 20831839, 2010). "Further, it has been shown that AR positive breast cancer patients have prolonged survival and a better response to hormone treatment than AR negative patients." (PMID 20831839, 2010). "By binding to a subset of EREs, the AR can prevent activation of target genes that mediate the stimulatory effects of 17β-estradiol on breast cancer cells." (PMID 20831839, 2010). "All these findings highlight the role of ER, PR and AR in promoting breast cancer and consequently their potential as drug targets in both preventive and therapeutic settings." (PMID 22276018, 2009). "Androgen receptors (AR) are expressed by the majority of human breast carcinomas, at a frequency comparable to or higher than that reported for ER and PR." (PMID 22276018, 2009). "We discuss the therapeutic implications of cross-talk between AR and members of the ErbB family in molecular apocrine type breast cancer." (PMID 19747394, 2009). "Other authors have also found that breast cancer patients with AR-negative tumors show a trend toward a shorter overall survival than those patients with AR-positive tumors." (PMID 18507821, 2008). "Our results confirm that AR are commonly expressed in breast cancer, and are correlated with the expression of some MMPs and TIMP-2." (PMID 18507821, 2008). "Our results confirmed previous biochemical and immunohistochemical studies indicating that AR are expressed in a considerable proportion of breast carcinomas." (PMID 18507821, 2008). "Our results confirm that AR are commonly expressed in breast cancer, and correlate with the expression of some MMPs and TIMP-2." (PMID 18507821, 2008). "Relationship between AR expression and different clinicopathological parameters in 111 breast carcinomas." (PMID 18507821, 2008). "Nevertheless, only a few studies have examined the impact of AR expression on patient prognosis in early breast cancer." (PMID 18507821, 2008). "We also found that AR expression in breast carcinomas is highly variable because of tumor heterogeneity." (PMID 18507821, 2008).
breast carcinoma (continued). "Although we found a specific value of AR expression to be a prognostic indicator in breast cancer, the functional role of AR in these neoplasms is still unclear and further data are needed in order to clarify their biological signification in breast cancer." (PMID 18507821, 2008). "Depending on the clinical correlation, including the status of ovaries and breast, AR positivity favors primary from mammary carcinoma and sometimes ovarian carcinoma." (PMID 17020615, 2006). "In our study there was a clear dominance of AR expression in mammary carcinoma compared to other adenocarcinomas." (PMID 17020615, 2006). "The underlying genetic variation was determined by first sequencing the coding regions of the AR gene in a panel of 95 advanced breast cancer cases." (PMID 16987421, 2006). "Simultaneous or isolated cytoplasmic staining with AR, ranging from weak to strong was noted in 62% (21/34) of these breast carcinomas." (PMID 17020615, 2006). "Data from further follow-up of the NHS and the WHS did not support the previous findings of interaction between the AR CAG repeat and family history on breast cancer risk in the NHS with follow-up to 1996." (PMID 16987421, 2006). "This study was undertaken to examine the expression of AR by immunohistochemistry in poorly differentiated primary breast carcinoma and adenocarcinomas from various other sites." (PMID 17020615, 2006). "Significant proportion of mammary carcinomas and some ovarian carcinomas express AR in the nuclei of more than 10% tumor cells." (PMID 17020615, 2006). "To better study the androgenic properties of synthetic progestins in breast cancer cells, we engineered T47D-Y cells to stably express wild-type AR." (PMID 16457685, 2005). "About 70–80% of all breast cancers express the androgen receptor, and androgens have been shown to have antiproliferative effects on breast cancer cell lines." (PMID 16100523, 2005). "Clinically, the complex pharmacology of MPA not only influences its side-effect profile; but it is also possible that the increased breast cancer risk and/or the therapeutic efficacy of MPA in cancer treatment is in part mediated by androgen receptor." (PMID 16457685, 2005). "We have found that HRG increases phosphorylation of Ebp1 in breast cancer cells and studies are underway in the laboratory to examine if enhanced phosphorylation of Ebp1 increases its binding to AR." (PMID 15583694, 2005). "To evaluate further the evidence for an association between AR CAG repeat length and breast cancer risk in BRCA1 and BRCA2 mutation carriers, we genotyped the polymorphism in a large series of female mutation carriers." (PMID 15743497, 2005). "One of these genes is p57, a cyclin-dependent kinase inhibitor with activity that suggests a possible mechanism for inhibition of cell cycle regulation and proliferation by AR in breast cancers." (PMID 16457685, 2005). "In vitro, they both stimulate (MCF-7, MDA-453) or inhibit (T-47D, ZR-75-1, MFM-223) the growth of AR-positive breast cancer cell lines." (PMID 12439719, 2002). "Androgen receptor (AR) expression was retrospectively analysed in 47 primary male breast carcinomas (MBCs) using a monoclonal antibody on formalin-fixed, paraffin-embedded tissues." (PMID 10070897, 1999). "Little is known regarding the activity and function of the androgen receptor (AR) in human breast cancer." (PMID 8883401, 1996). "In the present study AR was evaluated in untreated primary breast cancers using antisera to the amino- and carboxy-termini of the receptor and quantitated using colour video image analysis." (PMID 8883401, 1996). "This argues for patient stratification that systemically includes the AR and GR markers, in addition to ER and PR, as their activation may prove beneficial in the clinics for improving the treatment of patients with ER+ breast cancer metastasis." (PMID 41261233, 2026). "Evidence also supports antitumor activity of AR-targeted SARMs in selected breast cancer subtypes." (PMID 41752994, 2026).
breast carcinoma (continued). "Genes MYC and AR are known to be over-expressed in specific breast cancer subtypes, but this pattern was not proven for the entire, much more heterogeneous, cohort of TCGA breast cancer samples." (PMID 40724805, 2025). "Interestingly, canine mammary tumors also express ARs, making them a valuable model in which to study the cross-species relevance of AR signaling in breast cancer." (PMID 40286049, 2025). "AR has different signaling pathways that contribute to breast cancer pathogenesis." (PMID 39851328, 2025). "In contrast to other breast cancer subtypes, AR-TNBC remains underexplored." (PMID 40448099, 2025). "Studies have shown that AR signaling may stimulate or inhibit breast cancer growth, depending on the molecular subtype of the tumor." (PMID 40286049, 2025). "Leveraging findings from comparative studies, like those examining GATA-3 expression in canine mammary tumors—where it has shown correlations with favorable prognostic factors—can provide additional layers of understanding regarding the potential implications of AR expression in human breast cancer." (PMID 40286049, 2025). "High AR expression may have an adverse effect on the prognosis of tamoxifen treatment for ERα-positive breast cancer, as increased AR expression may potentially enhance the agonistic properties of tamoxifen." (PMID 41301715, 2025). "AR signaling in breast cancer, both in humans and in canines, is influenced by hormonal factors, and it is thought that ARs may interact with other hormonal receptors, including estrogen and progesterone receptors." (PMID 40286049, 2025). "In addition, the AR is a steroid hormone receptor widely detected in breast cancer, and approximately 80–95% of all ER+ breast cancers overexpress this receptor." (PMID 39857947, 2025). "Furthermore, gene expression analysis has confirmed that HER2-low breast cancers have a decreased expression of proliferation-related genes, tyrosine kinase receptor genes, and androgen receptor." (PMID 41316049, 2025). "Interestingly, all AIs (10 μM) act as androgen receptor (AR) agonists and modulate ER levels, synthesis and signaling to induce the apoptosis of ER+ breast cancer cells." (PMID 39857947, 2025). "Approximately 40% of breast cancer brain metastases also express the a AR." (PMID 41562063, 2025). "Therefore, understanding the interactions between ARs and these co-regulators is essential for determining the impact of AR signaling on breast cancer pathogenesis." (PMID 40286049, 2025). "While the exact mechanisms by which androgens exert their effects on breast cancer cells are still being elucidated, studies have shown that targeting androgen-receptor signaling may provide a novel therapeutic approach for both human and canine patients." (PMID 40286049, 2025). "AR shows context-dependent roles in ER breast cancers that loss of ARID1A disrupts chromatin regulators affecting drug sensitivities and self-regulation of ER; thus, future investigation of ARID1A-AR interactions across breast cancer subtypes is necessary." (PMID 41514650, 2025). "Interestingly, studies have shown a complex interplay between AR expression and the aggressive behavior of breast cancer cells, suggesting a dual role in tumor progression." (PMID 40286049, 2025). "Additionally, AR signaling has been implicated in the epithelial-to-mesenchymal transition (EMT), a key process that drives breast cancer cell invasion and metastatic spread." (PMID 40286049, 2025). "In addition, there is a long history of experience using anti-androgen/AR agents in male prostate and female breast cancers, making it an appealing target to investigate in other hormone driven cancers." (PMID 40392873, 2025). "Research into anti-androgen therapies, such as enzalutamide or bicalutamide, in canine mammary tumor models may provide insights into their effectiveness in treating AR-positive breast cancers in humans." (PMID 40286049, 2025).
breast carcinoma (continued). "Additionally, the dual role of AR as a tumor suppressor in ER+ve breast cancer and a contributor to DOX resistance via DNA repair poses a logical complexity." (PMID 40940753, 2025). "This variability complicates the interpretation of the AR’s role in breast cancer when relying solely on the immunohistochemistry-based expression data and could underly conflicting reports on the prognostic value of AR expression in TNBC." (PMID 40150035, 2025). "Evidence suggests that the AR might act as a tumor suppressor in ER+ breast cancer or a tumor promoter in ER- tumors." (PMID 39857947, 2025). "Several PROTACs are developed to target cancer drivers like the androgen receptor (AR) and estrogen receptor (ER), and they have entered phase I/II clinical trials for metastatic prostate and breast cancer, respectively, showing encouraging signs of target degradation and clinical activity." (PMID 41385185, 2025). "Like AR in PC, ERs drive a large subset of breast cancers that are treated with hormone therapies." (PMID 40282446, 2025). "Hormonal therapies targeting the androgen receptor or its downstream signaling pathways may offer therapeutic strategies for conditions such as androgen-sensitive breast cancers or mammary gland neoplasms." (PMID 40286049, 2025). "AR expression was strongly associated with ER positivity, with 83.1% of ER-positive cases also being AR-positive (p < 0.001), highlighting a robust link between AR- and ER-positive breast cancers that remained statistically significant after Bonferroni correction." (PMID 40734715, 2025). "The role of the androgen receptor (AR) in breast cancer (BC) remains incompletely understood." (PMID 40593140, 2025). "Despite extensive research, the exact roles of AR and TANs in breast cancer remain unclear, and results are often conflicting, particularly regarding their influence on tumor aggressiveness, response to therapy, and overall prognosis." (PMID 40734715, 2025). "Moreover, through a MetaCore functional enrichment analysis, GNPDA1 and SLC25A16 were associated with the BRCA1, BRCA2, and pro-oncogenic actions of the androgen receptor in breast cancer." (PMID 40278313, 2025). "Regarding RNF220 upregulation, multi-database analysis identified FOXA1 as a negative transcriptional regulator—this epigenetic modulator directly binds androgen receptor promoters, serves as an ER+ breast cancer biomarker, and drives progression in prostate/breast cancers via mutational activation." (PMID 41244923, 2025). "In addition, CBP/EP300 also activates transcription of the androgen receptor (AR) and thus promotes AR signaling in AR-positive breast cancer model MDA-MB-453 in vitro and in vivo." (PMID 40165290, 2025). "It has been demonstrated that AR activation can suppress ER+ve breast cancer." (PMID 40940753, 2025). "AR is frequently expressed in normal breast epithelial cells and is considered one of the markers of mammary epithelial cell differentiation and a favorable prognostic factor in breast cancer patients." (PMID 41373615, 2025). "The effect of AR on DNA repair in ER+ve breast cancer, however, remains to be addressed, and it is unclear whether AR inhibition can compromise doxorubicin resistance in ER+ve breast cancer." (PMID 40940753, 2025). "Moreover, AR-positive ER-positive breast cancers have been shown to respond better to endocrine therapies such as selective estrogen receptor modulators (SERMs) or aromatase inhibitors." (PMID 40286049, 2025). "With continued research, androgen receptor-targeted strategies could become an integral part of personalized treatment regimens for breast cancer in both species, improving outcomes and quality of life for patients." (PMID 40286049, 2025). "They defined AR overexpression as a new mechanism of hormone resistance and thus stated that AR could be a new clinical therapeutic target in human breast cancers." (PMID 40870508, 2025).
breast carcinoma (continued). "The molecular characterization of AR expression in canine mammary tumors could provide a model for investigating novel AR-targeted therapies." (PMID 40286049, 2025). "In canine mammary tumors, AR expression is often observed in both benign and malignant tumors, although its expression patterns may differ depending on the tumor’s histological subtype." (PMID 40286049, 2025). "In canine mammary tumors, elevated AR expression may similarly serve as an indicator of more aggressive tumor behavior, facilitating early detection and providing valuable prognostic information for veterinarians." (PMID 40286049, 2025). "Conversely, AR expression in canine mammary tumors is a relatively underexplored area of research." (PMID 40286049, 2025). "Given the similarities in tumor biology and treatment responses, canine mammary tumors serve as a valuable preclinical model for testing androgen receptor-targeted therapies and further understanding the molecular mechanisms driving both benign and malignant mammary tumors in dogs and humans alike." (PMID 40286049, 2025). "Canine mammary tumors, which are one of the most common neoplasms in female dogs, may also be influenced by AR signaling." (PMID 40286049, 2025). "Additionally, androgen treatment stimulated Akt and PI3K activation via AR- and proto-oncogene tyrosine protein kinase (Src)-dependent mechanisms within prostate and breast cancer cell lines." (PMID 40269952, 2025). "A comparative analysis of AR expression in human and canine mammary tumors could provide valuable insights into the shared and divergent mechanisms governing tumor development and progression in both species." (PMID 40286049, 2025). "In the context of canine mammary tumors, targeting ARs with these or similar agents may offer a promising therapeutic strategy, particularly for AR-positive, hormone receptor-positive tumors." (PMID 40286049, 2025). "Moreover, comprehensive assessments of androgen receptor (AR) expression across all breast cancer subtypes have shown that AA women are more likely to lack AR expression, with the highest frequency of AR loss seen in TNBC." (PMID 39769441, 2024). "However, further studies are needed to find the exact role and efficacy of AR-targeted therapies in various molecular subtypes of breast cancer." (PMID 39497884, 2024). "Furthermore, both genetic and pharmacological inhibition of USP14 significantly suppressed the growth of AR-reactive breast cancer cells by impeding the G0/G1-S phase transition and inducing apoptosis." (PMID 38383348, 2024). "Hence, a prospective multi-institutional study with a larger sample size is required to validate the prognostic significance of AR in breast cancer." (PMID 39497884, 2024). "The data suggest a limited role of AR IHC for the distinction of tumors and a strong prognostic role in breast cancer and clear cell RCC and highlight numerous tumor entities that could benefit from androgen-targeting cancer drugs." (PMID 38790919, 2024). "We and others report AR SUMOylation regulates AR function as our collective whole animal and cell-based studies demonstrate that a disruption of dynamic AR SUMOylation directs aberrant proliferation of prostate and breast cancer cells." (PMID 38327870, 2024). "Certain previous studies have demonstrated AR expression with favorable outcomes in breast cancer." (PMID 39497884, 2024). "Indeed, AR and ER coexpression can determine the efficacy of hormone receptor-mediated radiosensitization in breast cancer." (PMID 39199690, 2024). "Interestingly, there is renewed interest in the role of the AR in breast cancer subtypes as either a therapeutic target or prognostic biomarker." (PMID 39088439, 2024). "However, although the androgen/AR signaling pathway in TAMs is crucial for prostate cancer progression, its direct role in regulating TAMs in breast cancer remains largely unexplored." (PMID 39682229, 2024).